ELANE (elastase, neutrophil expressed)
Description:
Serine protease that modifies the functions of natural killer cells, monocytes and granulocytes. Shows microbicidal activity in neutrophils by mediating cleavage and degradation of bacterial proteins. Capable of killing E.coli but not S.aureus in vitro; digests outer membrane protein A (ompA) in E.coli and K.pneumoniae. Involved for the formation of neutrophil extracellular traps (NETs): translocates into the nucleus downstream of MPO and mediates degadation of histone H4, thereby participating to chromatin decondensation. NETs are mainly composed of DNA fibers and are released by neutrophils to trap pathogens during inflammation. Inhibits C5a-dependent neutrophil enzyme release and chemotaxis. Promotes cleavage of GSDMB, thereby inhibiting pyroptosis. Promotes blood coagulation. Through the activation of the platelet fibrinogen receptor integrin alpha-IIb/beta-3, potentiates platelet aggregation induced by a threshold concentration of cathepsin G (CTSG). Cleaves and thus inactivates tissue factor pathway inhibitor (TFPI). (Microbial infection) Inhibited reversibly by S.aureus serine protease inhibitors Eap, EapH1 and EapH2, impairing microbicidal activity in neutrophils.
Synonyms: HLE; ELA2; NE; HNE; PMN-E; GE; SCN1
Tractability: Small molecule: a drug acting on it is in phase 2 or 3 trials; a structure with a bound ligand is known; a high-quality ligand is known; it has a binding pocket of medium quality; it belongs to a druggable protein family. Antibody: its Gene Ontology location is reachable by antibodies, with high confidence; UniProt predicts a signal peptide or a membrane-spanning region. PROTAC: its protein half-life has been measured; a small molecule that binds it is known. Other modalities: an approved drug acts on it.
Target class: Serine protease; Enzyme; Serine protease PA clan; Serine protease S1A subfamily; Protease
Chemical probes: BAY-678 (high quality), BI-5524 (high quality), Symplostatin 5
Gene: Protein-coding gene on chromosome 19 (850,951 to 856,247, forward strand). Ensembl gene ENSG00000197561.
Subcellular location: Cytoplasmic vesicle, phagosome; Lysosome; Cytolytic granule; Nucleus
Subcellular location (Human Protein Atlas): Vesicles; Golgi apparatus; Predicted to be secreted
Pathways (Reactome):
Extracellular matrix organization: Activation of Matrix Metalloproteinases; Collagen degradation; Degradation of the extracellular matrix
Immune System: Antimicrobial peptides; Neutrophil degranulation; Regulation of Complement cascade
Programmed Cell Death: Pyroptosis
Signal Transduction: Expression of NOTCH2NL genes
Gene Ontology:
Molecular function: cytokine binding; endopeptidase activity; heparin binding; peptidase activity; protease binding; protein binding; serine-type endopeptidase activity; transcription corepressor activity; serine-type peptidase activity
Biological process: biosynthetic process of antibacterial peptides active against Gram-negative bacteria; defense response to bacterium; negative regulation of chemokine production; negative regulation of heterochromatin formation; negative regulation of interleukin-8 production; negative regulation of transcription by RNA polymerase II; neutrophil extracellular trap formation; neutrophil-mediated killing of bacterium; neutrophil-mediated killing of fungus; neutrophil-mediated killing of gram-negative bacterium; neutrophil-mediated killing of symbiont cell; positive regulation of interleukin-8 production; positive regulation of smooth muscle cell proliferation; proteolysis; response to UV; acute inflammatory response to antigenic stimulus; extracellular matrix disassembly; intracellular calcium ion homeostasis; leukocyte migration involved in inflammatory response; negative regulation of chemotaxis; negative regulation of inflammatory response; phagocytosis; positive regulation of MAP kinase activity; protein catabolic process; pyroptotic inflammatory response; and 1 more
Cellular component: azurophil granule; cell surface; cytoplasm; extracellular exosome; extracellular matrix; extracellular region; neutrophil extracellular trap; nucleus; secretory granule; transcription repressor complex; azurophil granule lumen; cytosol; specific granule lumen; cytolytic granule; lysosome; phagocytic vesicle
Genetic constraint (gnomAD): Loss-of-function variants: 12 observed, 15.61 expected, observed/expected ratio (o/e) 0.77, 90% interval 0.49 to 1.25. The upper end of that interval is the gene's LOEUF score, 1.25, which puts it in group 5 of 6, group 1 being the genes least tolerant of losing a copy. Missense variants: 388 observed, 359.43 expected, observed/expected ratio (o/e) 1.08, 90% interval 0.99 to 1.17. Synonymous variants: 203 observed, 167.6 expected, observed/expected ratio (o/e) 1.21, 90% interval 1.08 to 1.36.
Gene-disease validity (ClinGen):
ClinGen rates the evidence that ELANE causes each of these diseases.
neutropenia (autosomal dominant): Definitive. A decrease in the number of neutrophils found in the blood.
Homologues: Orthologues: chimpanzee ELANE (99% identical), macaque ELANE (87% identical), mouse Elane (72% identical), dog ELANE (71% identical), rat Elane (71% identical), guinea pig ELANE (69% identical), pig ELANE (68% identical), tropical clawed frog prtn3 (45% identical). Paralogues in human: PRTN3 (51% identical), CELA3A (34% identical), CELA3B (34% identical), CELA2A (33% identical), CELA1 (33% identical), CELA2B (31% identical).
Diseases named in the same sentence as ELANE in open-access papers:
ELANE is named in the same sentence as 334 diseases in open-access papers, as found by Europe PMC text mining. Sharing a sentence is not in itself a finding about the gene and the disease. The quoted sentences say what the papers report.
emphysema (94 papers, 1997 to 2026). "It was reported that patients that lack alpha-1 antitrypsin (α1-Pi) which is the physiological inhibitor of PRTN3 and ELANE carries a high risk of developing emphysema." (PMID 33079950, 2020). "ELANE, a factor that contributes to a protease-antiprotease imbalance and may cause inflammatory lung illnesses, induces autophagy, which in turn induces lung epithelial cell apoptosis and pulmonary emphysema through the overexpression of PGF." (PMID 37312153, 2023).
COVID-19 (81 papers, 2020 to 2026). A disease caused by infection with severe acute respiratory syndrome coronavirus 2. "Our study represents the first to establish an association between these ELANE variants and COVID-19." (PMID 38226800, 2024). "We aimed to assess the association of single nucleotide variants (SNVs) within ELANE with COVID-19 and biochemical markers." (PMID 38226800, 2024). "Our data indicate that ELANE rs17216663T/C (Pro257Leu) lacks association with COVID-19 susceptibility or with biochemical markers." (PMID 38226800, 2024). "We also investigated whether the ELANE SNVs were associated to biochemical markers of COVID-19." (PMID 38226800, 2024). "It was also reported that serum levels of ELANE in COVID-19 patients were significantly higher than those in healthy subjects, and especially elevated in patients in intensive care units (ICU) compared to non-ICU patients." (PMID 38226800, 2024). "Taken together, these findings strongly imply a crucial role for ELANE in the pathogenesis of COVID-19." (PMID 38226800, 2024). "Despite research efforts, to explore ELANE variants in patients with COVID-19, as of now, no study has yet examined the potential association between ELANE SNVs and this infectious viral disease." (PMID 38226800, 2024). "ELANE is also an independent predictor of the computed tomography score of lung damage in COVID-19." (PMID 38226800, 2024). "Studies on COVID-19 patients indicate upregulation of ELANE in nasopharyngeal swabs." (PMID 38226800, 2024). "ELANE Pro257Leu exhibited a comparable distribution in both patients and controls, suggesting that this variant is not a risk factor for COVID-19." (PMID 38226800, 2024). "In conclusion, our data suggests that ELANE rs17223045C/T and rs3761007G/A SNVs may play a protective role against COVID-19." (PMID 38226800, 2024). "Our findings indicate that ELANE rs17223045C/T (C vs T: odds ratio [OR] 0.08, P ═ 0.005, and CC vs CT: OR 0.08, P ═ 0.005) and rs3761007G/A (G vs A: OR 0.38, P ═ 0.009, and GG vs GA: OR 0.40, P ═ 0.008) confer protection against COVID-19." (PMID 38226800, 2024). "Conversely, both ELANE rs3761007G/A and Asn130Asn were found to confer protection against COVID-19." (PMID 38226800, 2024). "For instance, while reducing the correlation between DEGs including IL10, CXCL8, NFKB1, ARG1, and SOD2, new strong associations appeared between ELANE, DEFA4, AZU1, CTSG, and LCN2, with an overall tendency to higher relationships amid neutrophil-mediated immunity genes in COVID-19 patients." (PMID 35269470, 2022). "Interestingly, sera of ELANE KO mice immunized with the adsorbed SARS-CoV-2 S1 protein vaccine reacted with the same B cell epitopes recognized by sera from convalescent COVID-19 patients." (PMID 34353890, 2021). "According to the high similarity between SARS-CoV-2 and SARS-CoV, ELANE expression-dependent neutrophilia might be the reason for pulmonary hemorrhages in COVID-19 patients." (PMID 32582303, 2020). "ELANE variants have not been previously examined in COVID-19 patients." (PMID 38226800, 2024). "On the other hand, we identified three ELANE haplotypes associated with COVID-19, and notably, two of these haplotypes (ACC and GTC), composed of the A allele of rs371007G/A and the T allele of rs17223045C/T, were found to be associated with protection against COVID-19." (PMID 38226800, 2024). "Furthermore, this suggests that ELANE serves as an indicator of COVID-19 activity." (PMID 38226800, 2024). "Another study found increased ELANE expression and NET formation in neutrophils from COVID-19 patients compared to healthy donors." (PMID 38226800, 2024). "defined a population of ‘developing neutrophils’ in subjects with COVID-19 that seemed to derive from plasmablasts and overlap in marker expression with immature neutrophils (i.e., MPO, ELANE)." (PMID 38022639, 2023).
COVID-19 (continued). "When the blood transcriptomic profiles of patients with mild COVID-19 were compared with the profiles from patients with moderate or severe COVID-19, CEACAM8, MMP8, ELANE, LTF, CEACAM6 and MPO were consistently amongst the top SDE genes, with levels increasing with severity and high LFCs." (PMID 35844004, 2022). "However, the exact expression of ELANE, ARG1, and CXCL1, as well as neutrophil counting in COVID-19 patients, should be investigated by further studies to shed further light on COVID-19 treatment." (PMID 32582303, 2020). "Furthermore, the genes ELANE, AZU1, MPO, PRTN3, CTSG, and TCN1 were shown to be significantly altered in patients with COVID-19, and our automatically prepared knowledge base highlights all of them as associated with COVID-19 with “medium” or “low” confidence." (PMID 33055059, 2020). "This enzyme is also reported to be involved in the inflammation of the lungs, and it could be hypothesized that the correlated expression of ELANE and ARG1 might deteriorate the hemorrhaging of the lungs in SARS-positive patients and, similarly, COVID-19 patients." (PMID 32582303, 2020).
Sepsis (58 papers, 2005 to 2025). Sepsis is defined as life-threatening organ dysfunction caused by a dysregulated host response to infection. "The expression level of ELANE was significantly higher in sepsis patients and associated with poor prognosis in our study." (PMID 36618365, 2022). "We report that a necrotizing soft-tissue infection with severe sepsis occurred in a patient with CN containing a novel mutation in the ELANE gene." (PMID 25880377, 2015). "Neutrophil elastase could cleave GSDMD and cause neutrophil death, and the level of ELANE was reported to be associated with the severity of sepsis." (PMID 36618365, 2022). "Prior time series analysis of septic patients identified three genes in the elastase family (ELANE, CTSG, PRTN3) and DEFA4 as candidate biomarkers for sepsis, while other studies likewise implicated NETosis genes including ALPL." (PMID 41385588, 2025). "In the sepsis group, FCGR1A and TLR5 were positively associated with survival compared to ELANE, IL1R2, RAB13, and RNASE3, which were adversely associated with survival." (PMID 39655195, 2024). "Previous studies found that ELANE was overexpressed in patients with sepsis and correlated with the severity of sepsis." (PMID 38912048, 2024). "Consistently, in our study, ELANE was found to be expressed at significantly higher levels in sepsis patients compared to non-sepsis critically ill patients." (PMID 38912048, 2024). "Meta-random-effects model analysis showed that elevated expression levels of ELANE, FCGR1A, IL1R2, and RNASE3 were associated with sepsis." (PMID 39655195, 2024). "Six core genes, ELANE, IL1R2, RAB13, RNASE3, FCGR1A, and TLR5, have been linked to sepsis prognosis." (PMID 39655195, 2024). "In the two groups of different expression trend modules, the core genes such as CD160, GATA2, GNLY, IL2RB and TGFBR3 were downregulated in the sepsis group, while genes such as ELANE, IL1R1, TLR5, FCGR1A, MAPK14 and PCSK9 were upregulated." (PMID 35332254, 2022). "In contrast, a significant increase in the transcription of CLEC4D (C-type lectin domain family 4 member D), GCA (grancalcin), and ELANE (elastase, neutrophil expressed) was reported in the sepsis group as compared to the control." (PMID 34594344, 2021). "ELANE also functions inneutrophil extracellular traps.Neutrophil dysfunction is known to promote sepsis, and the alterations ofchemokines, cytokines, as well as other mediators lead to neutrophil dysfunction insepsis." (PMID 33503200, 2021). "Sivelestat, a selective ELANE and PRTN3 inhibitor was shown to improve the mortality rates of patients with sepsis associated with acute respiratory distress syndrome and disseminated intravascular coagulation." (PMID 33374674, 2020). "Notably, we identified five key genes (LTF, LCN2, ELANE, MPO, CEACAM8) associated with sepsis using the intersections of the top genes identified by cytoHubba and greenyellow module genes of the WGCNA." (PMID 38912048, 2024). "This study suggests a critical role of LTF, LCN2, ELANE, MPO and CEACAM8 in sepsis and may provide potential diagnostic biomarkers and therapeutic targets for the treatment of sepsis." (PMID 38912048, 2024). "The relationship between the gene ELANE and sepsis outcomes showed the opposite trend (P < 0.05)." (PMID 35332254, 2022). "However, there were no changes in the expression levels of CTSC, CTSG, PRTN3 and ELANE in neutrophils during sepsis compared to those from healthy controls." (PMID 33868254, 2021). "Thus, the DE genes identified in this study, such as OLFM4, MME, CXCR2,CEACAM8, and ELANE, probably take part in pediatric sepsis development by regulationof neutrophil function." (PMID 33503200, 2021). "Furthermore, the hub genes TLR5, FCGR1A, ELANE, GNLY, IL2RB and TGFBR3, which may be associated with the prognosis of sepsis, and their negatively correlated microRNAs, were analysed." (PMID 35332254, 2022).
Sepsis (continued). "Our study, which pinpointed ELANE and MPO as important DEGs, may provide insights into targeting neutrophils for the treatment of sepsis to prevent the collateral damage to peripheral organs caused by sepsis." (PMID 31817302, 2019). "Genes such as CSF3, ELANE, F5, and GALT exhibited significant differential expression between sepsis patients and controls." (PMID 41194984, 2025). "Analysis of clinical prognostic data (dataset: GSE65682) in the context of sepsis revealed that the upregulation of ELANE, IL1R2, RAB13, and RNASE3 affected prognosis by reducing the survival rate of patients with sepsis." (PMID 39655195, 2024). "ELANE, IL1R2, RAB13, and RNASE3 promote cell death, whereas FCGR1A and TLR5 facilitate cell survival in sepsis." (PMID 39655195, 2024). "In both datasets, the expression level of AIM2, ELANE, and MYD88 were significantly higher in sepsis patients compared to healthy individuals, while the expression level of CHMP7, GZMB, and NLRP1 were significantly lower." (PMID 36618365, 2022). "ELANE, MPO and CD177 were among the highest expressed genes in transcriptome meta-analyses of sepsis whole blood transcriptomes." (PMID 34552111, 2021). "ELANE, MPO, CD177, OLFM4 and OLAH gene expression were found to be comparable in both the groups sepsis and sterile inflammation indicating that neutrophil response to both bacterial infection and tissue injury involved upregulation of these genes." (PMID 34552111, 2021). "The DEGs (IL1R2, ARG1, FCGR1A, MMP9, ELANE, and MPO) that were common on day1 and day3 of sepsis, with at least 2.0-fold upregulation, were selected for constructing and visualizing the PPI network using Cytoscape." (PMID 31817302, 2019). "In addition, the expression levels of LTF, LCN, ELANE, MPO, and CEACAM8 were all up-regulated in the peripheral blood of sepsis patients than critical controls in the GSE131761 dataset, which is consistent with the previous findings." (PMID 38912048, 2024). "Subsequently, based on an external validation cohort from our hospital, qRT-PCR demonstrated significant up-regulation on LTF, LCN2, ELANE, MPO, and CEACAM8 in peripheral blood of sepsis patients versus controls, thus further enhancing the reliability of the findings." (PMID 38912048, 2024). "In summary, our investigation conducted comprehensive bioinformatics analysis on two gene datasets (GSE28750 and GSE74224) and discerned LTF, LCN2, ELANE, MPO and CEACAM8 as key up-regulated genes in sepsis patients when compared with non-sepsis critically ill controls." (PMID 38912048, 2024). "Moreover, previous transcriptomic studies have been published about identifying ELANE as an important signature related to the severity (SOFA score), and prognosis, of sepsis patients." (PMID 36911395, 2023). "Then, we developed a prognostic risk score with six pyroptosis-related genes, including GZMB, CHMP7, NLRP1, MYD88, ELANE, and AIM2, and found that it could predict the prognosis of sepsis patients." (PMID 36618365, 2022). "Consequently, the genes TLR5, FCGR1A, ELANE, GNLY, IL2RB and TGFBR3 genes were ultimately identified as hub genes in sepsis." (PMID 35332254, 2022). "We also found a higher expression of ELANE and MMP9 in sepsis." (PMID 31817302, 2019). "Administration of ELANE and CTSG induces lung inflammation, whereas knockout of both ELANE and CTSG decreases mortality rate and lung injury in a murine sepsis model." (PMID 30174607, 2018). "In summary, these findings suggest that ELANE, IL1R2, RAB13, RNASE3, FCGR1A, and TLR5 may influence the prognosis of patients with sepsis and provide novel insights and potential avenues for the treatment of sepsis." (PMID 39655195, 2024).
Sepsis (continued). "Importantly, our findings indicate that high expression levels of ELANE, IL1R2, RAB13, and RNASE3 promote death rates in sepsis, whereas high expression levels of FCGR1A and TLR5 improve the survival rate of patients with sepsis." (PMID 39655195, 2024). "Therefore, DEFA4, ELANE, MPO, and TFRC might be related to immune paralysis in sepsis." (PMID 36532037, 2022). "Finally, the expression of the topmost upregulated genes (ARG1, IL1R2, ELANE, MMP9) was quantified by reverse transcriptase-PCR (RT-PCR), and myeloperoxidase (MPO) expression was confirmed by immunohistochemistry (IHC) staining in the lungs of a well-established sepsis mouse model." (PMID 31817302, 2019).